PLA1A (phospholipase A1 member A)
Description:
Hydrolyzes the ester bond of the acyl group attached at the sn-1 position of phosphatidylserines (phospholipase A1 activity) and 1-acyl-2-lysophosphatidylserines (lysophospholipase activity) in the pathway of phosphatidylserines acyl chain remodeling. Cleaves phosphatidylserines exposed on the outer leaflet of the plasma membrane of apoptotic cells producing 2-acyl-1-lysophosphatidylserines, which in turn enhance mast cell activation and histamine production (By similarity). Has no activity toward other glycerophospholipids including phosphatidylcholines, phosphatidylethanolamines, phosphatidic acids or phosphatidylinositols, or glycerolipids such as triolein (By similarity). [Isoform 2]: Hydrolyzes lyso-PS but not PS.
Synonyms: PS-PLA1; PSPLA1
Tractability: Antibody: its Gene Ontology location is reachable by antibodies, with high confidence; UniProt places it where antibodies can reach, with medium confidence; UniProt predicts a signal peptide or a membrane-spanning region.
Safety:
Unwanted effects reported when the protein is acted on. In parentheses: how it was acted on, where the effect was seen, and who reports it.
Formation, Liver fibrosis (inhibition; source: AOP-Wiki)
Gene: Protein-coding gene on chromosome 3 (119,597,808 to 119,629,816, forward strand). Ensembl gene ENSG00000144837.
Subcellular location: Secreted
Pathways (Reactome):
Metabolism: Acyl chain remodelling of PS
Gene Ontology:
Molecular function: phosphatidylserine lysophospholipase activity; phospholipase A1 activity; carboxylic ester hydrolase activity; lipase activity
Biological process: lipid catabolic process; lipid metabolic process; phosphatidylserine acyl-chain remodeling; phosphatidylserine metabolic process
Cellular component: extracellular region; acrosomal membrane
Genetic constraint (gnomAD): Loss-of-function variants: 23 observed, 28.72 expected, observed/expected ratio (o/e) 0.8, 90% interval 0.57 to 1.13. The upper end of that interval is the gene's LOEUF score, 1.13, which puts it in group 4 of 6, group 1 being the genes least tolerant of losing a copy. Missense variants: 370 observed, 386.74 expected, observed/expected ratio (o/e) 0.96, 90% interval 0.88 to 1.04. Synonymous variants: 151 observed, 146.18 expected, observed/expected ratio (o/e) 1.03, 90% interval 0.9 to 1.18.
Homologues: Orthologues: chimpanzee PLA1A (99% identical), macaque PLA1A (92% identical), dog PLA1A (84% identical), pig PLA1A (83% identical), rabbit PLA1A (83% identical), mouse Pla1a (81% identical), guinea pig PLA1A (78% identical), rat Pla1a (77% identical), tropical clawed frog pla1a (45% identical), zebrafish pla1a (40% identical), Drosophila melanogaster CG6296 (21% identical), Drosophila melanogaster CG6472 (20% identical), and 13 more. Paralogues in human: LIPH (30% identical), LIPI (30% identical), LIPC (27% identical), PNLIP (26% identical), PNLIPRP2 (26% identical), LIPG (26% identical), LPL (25% identical), PNLIPRP1 (25% identical), PNLIPRP3 (24% identical).